TNF (tumor necrosis factor)
Diseases named in the same sentence as TNF in open-access papers (continued):
Sharing a sentence is not in itself a finding about the gene and the disease.
cardiac hypertrophy (continued). "Finally, CTX use leads to myocardial hypertrophy, myocardial fibrosis, and changes in the expressions of some cytokines, such as IL-1β, TNF-α, and IL-10, which are likely to promote AF development." (PMID 30386232, 2018). "Additionally, in a murine model of pressure overload, genetic disruption of TNF-α hampered cardiac hypertrophy, dysfunction, and fibrosis." (PMID 29138670, 2017). "Although the effect of IL-1β on angiotensin II-dependent cardiac hypertrophy is unknown, data from clinical settings and experiments have indicated that IL-22-IL-22R1-IL-10R2 binding can regulate IL-6, IL-17, IL-1β, TNF-α, and IFN-γ expression." (PMID 29358851, 2017). "Furthermore, pentoxifylline (TNF-α blocker) within the PVN causes decreased arterial pressure and cardiac hypertrophy in ANG II-induced hypertension." (PMID 27452860, 2016). "The present study found that CTX produced massive change including cardiac hypertrophy, fibrosis, heart edema with inflammatory cell infiltration and the expression change of several cytokines such as IL-1β, TNF-α and promoting IL-10, which were antagonized by BAE." (PMID 26133371, 2015). "Also it was demonstrated that 5-HT2BR is essential for isoproterenol-induced cardiac hypertrophy, which is regulated by interleukin-6 (IL-6), interleukin-1β (IL-1β), and tumor necrosis factor α (TNFα) cytokine production by cardiac fibroblasts." (PMID 25667920, 2015). "TNF-α not only exacerbates inflammatory response through acting as a signal amplifier to induce other inflammatory cytokines production, but also contributes to myocardial hypertrophy and fibrosis, leading to LV remodeling and dysfunction." (PMID 23530831, 2013). "Recent studies have shown that NF-κB directly exerts its role or alternatively involved in G protein-coupled receptor agonist- or tumour necrosis factor α(TNFα)-induced cardiac hypertrophy and pathological remodeling and fibrosis and NF-κB inhibition attenuates cardiac hypertrophy." (PMID 23349709, 2013). "Similarly, after using the NF-κB inhibitor BAY11-7082, both the cardiac hypertrophy and the increased expression of NF-κB, TNF-α, c-fos were reversed remarkably." (PMID 19210763, 2009). "Similarly, emodin is reported for cardioprotection via downregulating the TNF-α, NF-κB, and caspase-3 signaling pathways and effectively produced; vasorelaxation, anti-inflammatory, antithrombotic, anti-myocardial hypertrophy, anti-oxidative damage, antihypertensive and diuretic effects." (PMID 35684321, 2022). "Interestingly, one of the cytokines involved, TNF-α, exerts antioxidant and antiapoptotic effects in the myocardium at physiological levels, but when levels increase, it stimulates myocyte apoptosis, cardiac hypertrophy, and fibrosis." (PMID 34073506, 2021). "In addition, resistance training was able to reduce myocardial hypertrophy (P<0.05), left ventricular total collagen volume fraction (P<0.01), IL-6 (P<0.05), and TNF-α/IL-10 ratio (P<0.05), as well as increasing IL-10 (P<0.05) in chronic heart failure rats when compared to the S-CHF group." (PMID 25340545, 2014). "We found that CA ameliorated cardiac inflammation and myocardial hypertrophy after RH by regulating the expressions of IL-17, TNF α, MMP9, and COX2 in both the IL-17 and TNF signaling pathways." (PMID 39337549, 2024). "Meanwhile, deficiency of TIMP3 has been found capable to suppress Ang II-induced cardiac hypertrophy, but to enhance pressure overload-induced DCM primarily due to increased activity of ADAM17, TNFα and MMPs." (PMID 37057103, 2023). "Previous studies have demonstrated the important roles of interferon-gamma (IFN-γ), tumor necrosis factor-α (TNF-α), interleukin-1beta (IL-1β), and IL6 in cardiac hypertrophy and dysfunction." (PMID 37554327, 2023). "The release of inflammatory cytokines such as TNF-α, IL-1β, IL-6, and IL-8, and the production of inducible nitric oxide synthase (iNOS) and cyclooxygenase-2 (COX-2), can lead to cardiac hypertrophy and impaired cardiac function." (PMID 35276939, 2022).
cardiac hypertrophy (continued). "According to our previous studies, BSJY can promote the expression of the ERK pathway and inhibit the expression of the TNF-α, MCP-1, and IL-6, which would suppress ventricular hypertrophy and inflammatory responses." (PMID 35033168, 2022). "AngII-induced myocardial hypertrophy in WT mice with increased serum CK, LDH, IL-6, and TNF-α levels compared with the control group." (PMID 36046685, 2022). "The JAK/STAT pathway also transduces signals for a wide array of cytokines and growth factors including ANGII, TNF-α, IL-1β, IL-6 and IFN-γ, all of which have been involved in cardiac hypertrophy." (PMID 34225646, 2021). "In contrast to detrimental effects of soluble tumor necrosis factor-alpha (TNF-α) via TNFR1, this study shows that transmembrane TNF-α protects the heart by suppressing pressure overload-induced cardiac hypertrophy and inflammation via TNFR2." (PMID 33270628, 2020). "In the ISO-induced cardiac hypertrophy rat model, COX-2 was highly expressed, accompanied by elevation of cardiac NF-κB, TNF-α, and IL-6." (PMID 32848764, 2020). "Calcitriol supplementation in PAN-NS prevented cardiac hypertrophy, fibrosis, and inflammation, namely, by downregulating ET-1a, TGF-β1, and TNF-α genes and protein expression." (PMID 29607318, 2018). "Various stimuli are known to induce myocardial hypertrophy, myocardial fibrosis and apoptosis including neurohormonal factors and cytokines, such as AII, ET-1, TNF-α activation of redox-sensitive protein kinases and mechanical stretch." (PMID 26512646, 2015). "In a mice model of CVB3-induced viral myocarditis and pressure overload-induced cardiac hypertrophy, CTSB was upregulated in cardiomyocytes and promoted cardiac inflammation and dysfunction through activating the inflammasome or TNF-α/ASK1/JNK apoptotic signaling pathway." (PMID 41277866, 2026). "Additionally, ALKBH5 mediates the demethylation of STAT3 and regulates the expression of inflammatory factors (such as IL-6 and TNF-α) by activating the JAK2/STAT3 signaling pathway, thereby affecting the progression of cardiac hypertrophy." (PMID 40290189, 2025). "Pressure overload-induced cardiac hypertrophy in mice was found to increase myocardial IL-6 and IL-1β levels, although TNFα levels were not affected." (PMID 38256155, 2024). "In patients with obstructive HCM undergoing nonsurgical septal reduction, TNFα expression was decreased along with regression of cardiac hypertrophy." (PMID 38256155, 2024). "Interestingly, nanoceria significantly diminished the expression of genes related to cardiac hypertrophy (BNP, ANP, and β-MHC) and pro-inflammatory signaling (IL-1β, TNF-α, and iNOS) in H9c2 cells." (PMID 37107252, 2023). "After the gene was knocked out, it reduced cardiac-related inflammatory factors such as IL-6 and IL-1β, TNF-α and so on, which may be mainly through NF-κB and MAPK signaling pathways to regulate the production of myocardial hypertrophy." (PMID 36064568, 2022). "In addition, these cytokines are also involved in mediating cardiac remodeling as evidenced by the finding that genetic deletion of the TNF-α gene leads to a reduction in TAC-induced hypertrophy, whereas infusion of IL-6 in rat induces cardiac hypertrophy." (PMID 33192505, 2020). "Experimental studies with mammalian cardiomyocytes showed that TNF exerts a direct inotropic negative effect, reduces viability of cardiomyocytes, enhances myocardial fibrosis and ventricular hypertrophy." (PMID 29895751, 2018). "Angiotensin (Ang) II, platelet-derived growth factor (PDGF), and tumor necrosis factor (TNF)-α induce the production of ROS in the cardiac muscle through the NADPH oxidase and then cardiomyocytes apoptosis, cardiac hypertrophy, reduction of myofilament sensitivity and cardiac contractility." (PMID 28531112, 2017). "LXR activation may inhibit NF-κB and its downstream inflammatory cytokines, such as IL-T, TNF-α, and iNOS, which could improve PAH-induced cardiac hypertrophy and remodeling." (PMID 28733583, 2017).
cardiac hypertrophy (continued). "TLR4 inhibition within the PVN attenuated MAP, improved cardiac hypertrophy, reduced TNF-α, IL-1β, iNOS levels, and NFκB activity in SHR but not in WKY rats." (PMID 25879545, 2015). "In mouse and human models of pathological myocardial hypertrophy leading to cardiac dysfunction, ERK1/2, SAPK/JNK, and p38 MAPK are activated and increased in the heart, and these pathways further increase the expression of inflammatory mediators (TNF, IL-6) and hypertrophic factors (ET-1)." (PMID 40997050, 2025). "Specific targeting of tmTNF-α processing, rather than anti-TNF therapy, may be more useful for the treatment of hypertrophy and HF." (PMID 33270628, 2020). "Foxm1 deletion did not alter mRNA expression of genes critical for cardiac hypertrophy and fibrosis such as α-SMA, collagen 1α1, CaMKIIδ, TNFα, BMP4, MMP9, CXCR4 and Hey2." (PMID 23144938, 2012).
gout (181 papers, 2007 to 2026). A condition characterized by painful swelling of the joints, which is caused by deposition of urate crystals. "Collectively, AATF exerts anti-gout effects through multi-target and multi-pathway mechanisms linked to the TNF signaling pathway, providing critical preliminary evidence for its preclinical development." (PMID 42317507, 2026). "In total, three candidate targets including KCNA5, PTGS2, and TNF were identified as having genetic causality with gout and were selected for further analysis as critical targets." (PMID 40430440, 2025). "Bai Su Geng contains phenolics, coumarins, terpenoids, and alkaloids that mitigate gout‐associated inflammation and oxidative stress by suppressing IL‐1β/TNF‐α and scavenging free radicals." (PMID 40613560, 2025). "Activation of the NLRP3 inflammasome has been implicated in the pathogenesis of gout, leading to the production of inflammatory cytokines such as IL-1β, IL-6, and TNF-α." (PMID 39907694, 2025). "These compounds inhibit the production of proinflammatory cytokines and enzymes, such as TNF-α, IL-1β, and cyclooxygenase-2, key contributors to the inflammatory response associated with gout." (PMID 39409183, 2024). "The ointment contains herbal components such as Aconitum carmichaelii and Notopterygium incisum, which inhibit key inflammatory mediators, including TNF-α, IL-1β, and IL-6, thereby reducing acute pain and swelling associated with gout flares." (PMID 39409183, 2024). "The formula contains bioactive compounds that inhibit inflammatory cytokines such as TNF-α, IL-1β, and IL-6 and enhance renal excretion of uric acid, providing both symptomatic relief and addressing the underlying causes of gout." (PMID 39409183, 2024). "This modulation aids in alleviating symptoms linked to MSU-induced gouty arthritis, such as neutrophil infiltration in knee joints, joint circumference and the production of TNF-α, IL-1β, IL-6, and IL-18." (PMID 38094893, 2023). "In order to further investigate the changes in inflammatory factors associated with gout, the expression levels of IL-1β, IL-6, and TNF-α were re-examined in serum." (PMID 37771709, 2023). "Previous studies have shown that IL-6, IL-1β, and TNF-α were associated with inflammatory activity in patients with gout." (PMID 35145506, 2022). "The expression levels of three pro-inflammatory cytokines (i.e., IL-1β, IL-6, and TNF-α) associated with gout were further investigated in serum." (PMID 35145506, 2022). "Pro-inflammatory cytokines have been implicated in initiation and amplification of the gout flare, such as IL-1β, IL-6, and TNF-α." (PMID 34586567, 2022). "Neutrophils correlate with the elevation of IL-1β, IL-8, and TNF-α levels, which are necessary cytokines in inflammation and significant mediators implicated in the pathogenesis of gout." (PMID 36286462, 2022). "Molecular studies have shown that the polymorphism in the promoter region of TNF-α gene promotes the development of gouty arthritis." (PMID 34359507, 2021). "The first inflammatory modulating gene associated with gout was TNF-α in a Taiwanese cohort of patients." (PMID 33926105, 2021). "For instance, the deposition of MSU crystals promotes the local release of TNF-α and IL-1β, which causes persistent gout episodes." (PMID 34007291, 2021). "Nucleated uric acid is able to stimulate the production of inflammatory cytokines such as IL-1, TNF-α, and IL-6 in gout, a classic disease caused by hyperuricemia." (PMID 33679237, 2021). "IL-1β along with other pro-inflammatory cytokines, TNF-α, IL-6, and IL-8 promote neutrophil influx, the primary pathological hallmark of gout." (PMID 26709520, 2015). "The release of IL-1β, IL-18 and TNF are tightly associated with the pathogenesis of gout." (PMID 39130631, 2024). "Physical activity may exert anti-inflammatory effects by lowering IL-6, reducing C-reactive protein, and inhibiting TNF-α, thereby reducing the risk of gout." (PMID 38276301, 2024).
gout (continued). "In addition, IL-6 was associated with inflammatory activity in gout, the presence of tophi and articular deformities and IL-10 down-regulated the inflammatory responses in gout through inhibition of TNF-α, MIP-1α, and MIP-1β in MSU crystal–stimulated cells." (PMID 38711064, 2024). "Monosodium urate crystal is the causative factor of gout, which can activate a variety of immune cells to release proinflammatory cytokines such as tumor necrosis factor-alpha (TNF-α) and interleukin-1 beta (IL-1β), thereby inducing the production of gouty arthritis." (PMID 34803702, 2021). "A number of researchers have confirmed that gout shares many pathogenetic features associated with other inflammatory disorders, i.e. a rapid increase in the secretion of some pro-inflammatory cytokines (IL-1β, IL-6 and TNF-α)." (PMID 32041665, 2020). "In addition, direct effects of pioglitazone in a rat model of gout have been reported and associated with reduced synovial cytokine (TNFα, IFN-γ and IL-1β) levels." (PMID 30202096, 2018). "A possible explanation for these observations is that patients with gout present with monosodium urate crystal-mediated inflammatory cytokines including tumor necrosis factor-α (TNF-α) and interleukin-1β (IL-1β), which have been implicated in the pathogenesis of myocardial dysfunction." (PMID 26568484, 2015). "In particular, the elevated levels of pro-inflammatory cytokines, such as IL-1β and TNF-α, in the synovial fluid of patients with gout, may be associated with miR-155-mediated regulation of monocyte/macrophage responses to MSU crystals." (PMID 24708712, 2014). "Furthermore, the reverse MR analysis suggests that elevated levels of CXCL1, IL-1Ra, and TNF-α may be a consequence of gout, with these associations remaining robust after sensitivity analysis." (PMID 40388724, 2025). "Sang Zhi bioactive components alleviate gouty arthritis by inhibiting NF‐κB signaling to reduce IL‐6/TNF‐α release, thereby ameliorating local inflammation and pain." (PMID 40613560, 2025). "Neutrophils residing in joints, upon encountering MSU crystals, undergo activation, phagocytose crystals, and release inflammatory mediators including IL-1β, TNF-α, and IL-6, thereby intensifying acute inflammatory gout flares." (PMID 40612947, 2025). "Compared with the normal group, the PTGS2 and TNF expression levels were dramatically higher in the gout group, and the expression of KCNA5 was prominently lower in the gout group." (PMID 40430440, 2025). "Bai Su Zi is rich in α‐linolenic acid (ALA, > 65% in Perilla seeds), an ω‐3 polyunsaturated fatty acid that alleviates gouty arthritis by modulating lipid metabolism, inhibiting IL‐6/TNF‐α, and promoting anti‐inflammatory mediators like lipoxins." (PMID 40613560, 2025). "This study also confirms the positive correlation between TNF-α and gout, offering valuable insights for future drug development and clinical research." (PMID 40388724, 2025). "Hypermethylation of promoter regions in anti-inflammatory genes such as IL-10, and hypomethylation in pro-inflammatory loci, such as TNF, have been identified in patients with chronic gout." (PMID 40612947, 2025). "Consistent with the acute gout model, the Young + Old or Young + Aged group exhibited more pronounced activation of IL-1β, IL-6, and TNF-α in peritoneal fluid and serum." (PMID 39907694, 2025). "In the LOO analysis, it was discovered that no single SNP strongly altered the holistic forest plot of KCNA5, PTGS2, and TNF for gout." (PMID 40430440, 2025). "Immunohistochemical analysis showed a substantial upregulation in the expression of pro‐inflammatory markers, including TNF‐α, IL‐6, and IL‐1β, in the paw tissues of gout mice compared to the control group." (PMID 39717013, 2025).